PCIF1 (phosphorylated CTD interacting factor 1)
Description:
Cap-specific adenosine methyltransferase that catalyzes formation of N(6),2'-O-dimethyladenosine cap (m6A(m)) by methylating the adenosine at the second transcribed position of capped mRNAs. Recruited to the early elongation complex of RNA polymerase II (RNAPII) via interaction with POLR2A and mediates formation of m6A(m) co-transcriptionally.
Synonyms: CAPAM; hCAPAM; hPCIF1; C20orf67; PPP1R121; bA465L10.1; MT-A70
Tractability: Small molecule: a structure with a bound ligand is known. PROTAC: ubiquitination databases record sites on it; its protein half-life has been measured.
Target class: Enzyme; Transferase
Gene: Protein-coding gene on chromosome 20 (45,934,678 to 45,948,023, forward strand). Ensembl gene ENSG00000100982.
Subcellular location: Nucleus
Subcellular location (Human Protein Atlas): Nucleoplasm; Cytokinetic bridge; Microtubules
Gene Ontology:
Molecular function: mRNA (2'-O-methyladenosine-N6-)-methyltransferase activity; RNA polymerase II C-terminal domain binding; RNA polymerase II C-terminal domain phosphoserine binding; S-adenosyl-L-methionine binding
Biological process: mRNA processing; negative regulation of translation; positive regulation of translation; regulation of translation
Cellular component: intercellular bridge; microtubule cytoskeleton; nucleoplasm; nucleus
Genetic constraint (gnomAD): Loss-of-function variants: 12 observed, 84.88 expected, observed/expected ratio (o/e) 0.14, 90% interval 0.09 to 0.23. The upper end of that interval is the gene's LOEUF score, 0.23, which puts it in group 1 of 6, group 1 being the genes least tolerant of losing a copy. Missense variants: 701 observed, 973.7 expected, observed/expected ratio (o/e) 0.72, 90% interval 0.68 to 0.77. Synonymous variants: 397 observed, 381.67 expected, observed/expected ratio (o/e) 1.04, 90% interval 0.96 to 1.13.
Homologues: Orthologues: macaque PCIF1 (99% identical), chimpanzee PCIF1 (99% identical), dog PCIF1 (98% identical), pig PCIF1 (98% identical), rabbit PCIF1 (97% identical), rat Pcif1 (96% identical), mouse Pcif1 (95% identical), guinea pig PCIF1 (94% identical), tropical clawed frog pcif1 (70% identical), zebrafish pcif1 (68% identical), Drosophila melanogaster Pcif1 (43% identical).
Diseases named in the same sentence as PCIF1 in open-access papers:
PCIF1 is named in the same sentence as 51 diseases in open-access papers, as found by Europe PMC text mining. Sharing a sentence is not in itself a finding about the gene and the disease. The quoted sentences say what the papers report.
gastric cancer (13 papers, 2021 to 2025). A primary or metastatic malignant neoplasm involving the stomach. "Our group found that PCIF1 expression was significantly elevated in gastric cancer tissues, which was associated with poorer overall survival in patients." (PMID 38509021, 2024). "Kaplan–Meier analysis of these PCIF1 target transcripts revealed that nine mRNAs were significantly associated with overall survival of gastric cancer patients." (PMID 35597784, 2022). "Increased PCIF1 is associated with gastric cancer progression, and predicts poor prognosis." (PMID 35597784, 2022). "For example, PCIF1 is involved in gastric cancer progression by inhibiting the mRNA translation of the tumor suppressor gene TM9SF1 via m6Am modification." (PMID 39451207, 2024). "Mechanistically, the upregulation of PCIF1 expression enhances gastric cancer cell proliferation and invasion by increasing the m6Am level of TM9SF1 mRNA to enhance its translation." (PMID 38509021, 2024). "For example, PCIF1 is a poor prognostic factor in gastric cancer and colorectal cancer, while it plays an anti-tumor role in bladder cancer and glioma." (PMID 37779183, 2023). "Using Cox analysis, PCIF1 was identified as an independent adverse prognostic factor for gastric cancer." (PMID 37779183, 2023). "According to studies, the circ-ATAD1/miR-140-3p/YY1/PCIF1 axis is essential for the growth of gastric cancer." (PMID 37779183, 2023). "Xu found that the expression levels of PD-L1 and PD-1 in gastric cancer tissue were significantly increased and correlated with PCIF1 through bioinformatics analysis." (PMID 37779183, 2023). "In recent research, PCIF1 expression was found to be significantly elevated, and PCIF1 seemed to play as an oncogene in digestive system tumors, including gastric cancer, CRC, esophageal carcinoma, and hepatocellular carcinoma." (PMID 39524541, 2023). "In 2022, PCIF1 was first reported to be aberrantly overexpressed in gastric cancer and plays an oncogenic role as an m6Am methyltransferase." (PMID 39524541, 2023). "The progression of gastric cancer is accelerated by increased methyltransferases driven by m6Am methylation changes (PCIF1)." (PMID 37880673, 2023). "For example, PCIF1 is tumorigenic in gastric cancer, colorectal cancer, and bladder cancer, while it is a tumor suppressor in glioma." (PMID 37779183, 2023). "In gastric cancer, the expression of PCIF1 is significantly increased, which can be used as an independent predictor of poor prognosis." (PMID 37779183, 2023). "In gastric cancer, PCIF1 suppresses TM9SF1 mRNA translation, contributing to tumor aggressiveness and metastasis." (PMID 37643007, 2023). "Silence of PCIF1 inhibits the proliferation and invasion of gastric cancer cells, and suppresses tumor growth and metastasis in mouse model." (PMID 35597784, 2022). "PCIF1 mRNA levels were higher in tumor tissues from patients with advanced gastric cancer than that of patients in early stages." (PMID 35597784, 2022). "Depletion of PCIF1 inhibits the proliferation and invasion of gastric cancer cells, and suppresses tumor growth and metastasis." (PMID 35597784, 2022). "Taken together, our data suggest that elevated expression of PCIF1 in gastric cancer tissues is an independent predictor for poor prognosis." (PMID 35597784, 2022). "Quantitative RT-PCR (qRT-PCR) confirmed that PCIF1 mRNA was significantly increased in tumor tissues from 123 gastric cancer patients (cohort Zhejiang)." (PMID 35597784, 2022). "PCIF1 was involved in aggressiveness of gastric cancer cells via suppression of TM9SF1 mRNA translation." (PMID 36003776, 2022). "Collectively, these results suggest that PCIF1 is essential for gastric cancer cell proliferation and invasion." (PMID 35597784, 2022). "Our data show that m6Am modification and PCIF1 expression are significantly increased in gastric cancer tissues." (PMID 35597784, 2022).
gastric cancer (continued). "Kaplan–Meier and multivariate COX analyses of cohort ACRG (Asian Cancer Research Group, GSE62254) confirmed that PCIF1 mRNA expression was also an independent poor prognostic factor for gastric cancer patients." (PMID 35597784, 2022). "Taken together, these data indicate that TM9SF1 is a functional downstream target of PCIF1 during gastric cancer development." (PMID 35597784, 2022). "To explore the biological roles of PCIF1 in gastric cancer progression, we depleted PCIF1 expression in AGS cells with two different lentivirus-based shRNAs." (PMID 35597784, 2022). "In this study, we identified that PCIF1 and m6Am modification levels in mRNAs are significantly upregulated in gastric cancer tissues." (PMID 35597784, 2022). "Here we find that both PCIF1 expression and m6Am modification are significantly elevated in gastric cancer tissues." (PMID 35597784, 2022). "The significant upregulation of PCIF1 levels in gastric cancer tissues prompted us to determine the correlation between PCIF1 expression and clinical outcomes." (PMID 35597784, 2022). "We integrate multiple approaches, including EGFP reporter assays, polysome profiling, m6Am-seq and western blotting, and find that the protein levels of some highly confident m6Am-contaning transcripts are increased in gastric cancer cells depleted of PCIF1." (PMID 35597784, 2022). "Considering PCIF1 was frequently upregulated in gastric cancer tissues, we overexpressed PCIF1 and found that the relative proportion of modified TM9SF1 mRNA was robustly increased to more than 70% in AGS cells." (PMID 35597784, 2022). "Silencing PCIF1 also enhanced the translation of its target mRNAs in BGC-823 gastric cancer cells." (PMID 38509021, 2024). "PCIF1 protein and m6Am levels were also found to be upregulated in gastric cancer cases (GC)." (PMID 36768600, 2023). "In gastric cancer, PCIF1 protein will increase in the late stage." (PMID 37779183, 2023). "Taken together, these data indicate that PCIF1 functions as an oncogene in gastric cancer." (PMID 35597784, 2022). "Moreover, we found that TM9SF1 (transmembrane 9 superfamily member 1) is a functional mRNA target of PCIF1 and acts as a tumor suppressor gene in gastric cancer." (PMID 35597784, 2022). "Furthermore, we examined PCIF1 protein expression in paraffin-embedded tumor tissues from 140 gastric cancer patients (cohort tissue array)." (PMID 35597784, 2022). "PCIF1 predicts a poor prognosis and plays an oncogenic role in gastric cancer development." (PMID 35597784, 2022). "Since PCIF1 is associated with gastric cancer aggressiveness and suppresses TM9SF1 mRNA translation, we continued to determine whether TM9SF1 mediates the oncogenic role of PCIF1 in gastric cancer progression." (PMID 35597784, 2022). "TM9SF1 reverses the effects of PCIF1 on gastric cancer cell aggressiveness." (PMID 35597784, 2022). "Furthermore, knockdown of TM9SF1 reverses the decreased malignancy induced by PCIF1 deletion in gastric cancer cells." (PMID 35597784, 2022). "YY1 then binds to PCIF1 promoter to upregulate PCIF1 and promote gastric cancer progression." (PMID 34857012, 2021). "In gastric cancer, colorectal cancer and bladder cancer, PCIF1 KO can reduce tumor migration, invasion and other malignant behaviors, reduce subcutaneous tumorigenesis, and even reduce lung metastasis, indicating that PCIF1 may be a target for tumor treatment in the future." (PMID 37779183, 2023). "In a novel circular RNA study, it was found that circ-ATAD1 regulates gastric cancer tumorigenesis and progression by up-regulating YY1, which directly binds to the promoter of PCIF1 and activates the transcription of PCIF1." (PMID 39524541, 2023). "The promoter domain of PCIF1 is attached directly by YY1, increasing transcription and advancing gastric cancer." (PMID 37779183, 2023).
gastric cancer (continued). "Mechanically, PCIF1 modifies TM9SF1 mRNA with m6Am to inhibit its mRNA translation, which reduces the protein levels of TM9SF1 to enhance gastric cancer cell malignancy." (PMID 35597784, 2022). "We silenced TM9SF1 in PCIF1-depleted gastric cancer cells with two independent shRNAs, and found that knockdown of TM9SF1 significantly reversed the inhibitory effects of PCIF1 depletion on cell invasion and cell proliferation." (PMID 35597784, 2022). "Our findings demonstrate that PCIF1 selectively represses MTF2 translation, leading to tumour progression, which aligns with the role of m6Am modifications as previously reported in several cancers, such as colorectal cancer, glioblastoma and gastric cancer." (PMID 40156159, 2025). "PCIF1 can modify TM9SF1 mRNA through m6Am and inhibit its mRNA translation, thus reducing the level of TM9SF1 protein, thereby promoting the development of gastric cancer." (PMID 37779183, 2023). "Multivariate COX analysis showed that high PCIF1 expression was an independent negative prognostic factor for predicting clinical outcome of gastric cancer patients." (PMID 35597784, 2022). "Wei also found that in gastric cancer cells, the half-life of AGS cells with PCIF1 KO did not change, indicating that PCIF1 did not affect mRNA transcription and stability changes." (PMID 37779183, 2023).
colorectal cancer (8 papers, 2021 to 2025). A primary or metastatic malignant neoplasm that affects the colon or rectum. "These colorectal cancer cells have high PCIF1 expression based on western blotting and RT-qPCR, while the non-cancerous colon cell line CCD841 CoN has very low PCIF1 expression." (PMID 39677659, 2025). "PCIF1 controls the stability of FOS mRNA in colorectal cancer cells through m6Am deposition, thereby regulating TGF-β transcription." (PMID 37779183, 2023). "Studies have shown that among 27 patients with colorectal cancer, 19 patients with low PCIF1 expression have a significantly longer survival time than 8 patients with high PCIF1 expression, indicating that the dose of PCIF1 is also related prognosis." (PMID 37779183, 2023). "Depletion of PCIF1 in colorectal cancer cells enhances the efficacy of anti–PD-1 treatment by modulating immune response factors and promoting tumor-infiltrating natural killer cell recruitment." (PMID 37643007, 2023). "Recently, Relier and colleagues have shown that inhibition of nuclear PCIF1-mediated m6Am modification in mRNA led to reduced colorectal cancer stem cell abilities, which was the first and the only study so far that revealed the role of m6Am of mRNA in cancer." (PMID 34888238, 2021). "Similarly, in colorectal cancer, PCIF1 has been found to stabilize transcript stability in response to anti‐immunotherapy." (PMID 40156159, 2025). "In colorectal cancer(CRC), PCIF1 is upregulated and associated with poor prognosis." (PMID 37779183, 2023). "Researchers have also verified the relationship between PCIF1 and immunity in colorectal cancer." (PMID 37779183, 2023). "PCIF1 can be an independent prognostic factor in gastric and colorectal cancers." (PMID 37779183, 2023). "Second, we selected colorectal cancer cells (i.e., HT-29 and HCT-116), since PCIF1 depletion in these cells affects their migration and sensitivity to immunotherapy." (PMID 39677659, 2025). "In colorectal cancer, phosphorylated CTD interacting factor 1 (PCIF1) modulates colorectal cancer growth and response to anti-programmed cell death 1 (PD-1) in a context-dependent mechanism in which PCIF1 directly targets FOS, IFITM3, and STAT1 via N6,2′-O-dimethyladenosine (m6Am) modifications." (PMID 40681213, 2025).
glioma (6 papers, 2022 to 2024). A benign or malignant brain and spinal cord tumor that arises from glial cells (astrocytes, oligodendrocytes, ependymal cells). "Moreover, PCIF1 overexpression causes cell cycle arrest at the G2/M phase and apoptosis in glioma cells." (PMID 39524541, 2023). "PCIF1 inhibits glioma cell proliferation both in vitro and in vivo, while its knockdown increases cell proliferation and cell cycle progression and reduces apoptosis." (PMID 39524541, 2023). "In this case, PCIF1 knockdown promoted the proliferation of primary glioma cells, glioma cell lines, and glioma xenograft mice." (PMID 36768600, 2023). "Overexpression of PCIF1 inhibits cell proliferation, blocks the cell cycle of glioma at G2/M phase, and induces apoptosis." (PMID 37779183, 2023). "The overexpression of m6Am methyltransferase PCIF1 in glioma blocks G0/G1 phase progression and induces glioma cell apoptosis, whereas the downregulation of PCIF1 promotes glioma cell proliferation." (PMID 36360287, 2022). "Intriguingly, PCIF1 has low expression levels in high-grade glioma tissues." (PMID 38509021, 2024). "Furthermore, increased PCIF1 levels in glioma cell lines impaired proliferation and promoted apoptosis, while overexpression of PCIF1 in glioma cells injected into the brains of mice reduced the growth of the tumors and extended the survival rates of the animals." (PMID 36768600, 2023). "However, recently, in gliomas a tumor suppressor role was again demonstrated for PCIF1." (PMID 36768600, 2023). "Overexpression of PCIF1, but not its catalytically inactive mutant, results in the repression of glioma cell proliferation." (PMID 38509021, 2024). "Though significant promoted cell proliferation can be observed in immortalized glioma cell line U251 when PCIF1 is significantly down-regulated, m6Am/A level has not been affected." (PMID 39524541, 2023). "Another study demonstrated that PCIF1 exerts suppressive effects on glioma growth and survival, which may not entirely depend on its methyltransferase activity." (PMID 37643007, 2023).
viral infection (4 papers, 2021 to 2024). "PCIF1 and its catalyzed m6Am modification have been implicated in various diseases, such as glucose homeostasis disorders, viral infections, obesity, and cancers." (PMID 39524541, 2023). "We further review the molecular mechanisms of PCIF1 in cancer and viral infection and discuss its therapeutic potential." (PMID 39524541, 2023). "To investigate which steps of the HIV life cycle are inhibited by PCIF1, we utilized two single-cycle viral infection systems and PCIF1 KO 293FT cells." (PMID 34545078, 2021). "However, recent studies have provided evidence that PCIF1-mediated m6Am modification is involved in a variety of biological processes, including stress response, viral infection, cancer, metabolism, and ciliogenesis." (PMID 39451207, 2024). "The recognition of the involvement of PCIF1 and m6Am modification in virus–host interactions, suggests that PCIF1 may be a promising therapeutic target for viral infections." (PMID 39524541, 2023). "However, further research is needed to explore its functional connections and differences with Nm, as well as the role of PCIF1 in viral infection." (PMID 37915585, 2023). "Altogether, our study discovers the role of PCIF1 in HIV–host interactions, identifies m6Am modified genes in T cells which are affected by viral infection, and reveals how HIV regulates host RNA epitranscriptomics through PCIF1 degradation." (PMID 34545078, 2021). "So far, the role of m6Am RNA modification and the catalytic function of PCIF1 in biological and disease processes, especially in regulating viral infections and host–pathogens interactions have not to be determined." (PMID 34545078, 2021).
thyroid cancer (3 papers, 2021 to 2023). "For example, PCIF1 expression is increased in gastric, colorectal and liver cancers, whereas it is decreased in breast, prostate and thyroid cancers." (PMID 35597784, 2022).
autoimmune disease (2 papers, 2022 to 2026). A disorder resulting from loss of function or tissue destruction of an organ or multiple organs, arising from humoral or cellular immune responses of the individual to their own tissue constituents. "In this study, we uncover a novel role for PCIF1 as a crucial negative regulator of type I interferon (IFN) induction, a pathway critical for antiviral immunity whose dysregulation leads to inflammatory and autoimmune diseases." (PMID 41677666, 2026).
bladder cancer (2 papers, 2021 to 2023). "Indeed, a genetic screen identified PCIF1/CAPAM as a putative tumor growth suppressor in bladder cancer." (PMID 33376192, 2021).
colon cancer (2 papers, 2021 to 2024). "We also analyzed differences in phosphorylation of PCIF1 among normal tissues and tumor lesions (OV, colon cancer, clear cell RCC, UCEC, breast cancer, and lung adenocarcinoma) based on CPTAC dataset." (PMID 34888238, 2021). "The S116, S159, and S144 loci of PCIF1 possessed a higher phosphorylation level in colon cancer tissues, but the phosphorylation level at the T150 locus was higher in normal tissues with statistical difference (p < 0.05)." (PMID 34888238, 2021). "Additionally, PCIF1 has been reported to regulate colon cancer growth and response to anti-PD-1 by stabilizing cancer-promoting gene mRNAs, such as FOS, IFITM3, and STAT1, through m6Am modifications." (PMID 39451207, 2024).
esophageal carcinoma (2 papers, 2023 to 2025). A primary or metastatic malignant neoplasm involving the esophagus. "PCIF1 was found to be significantly upregulated in several cancers, with particularly high expression observed in oesophageal cancer, suggesting its potential role in tumourigenesis." (PMID 40156159, 2025).